NES (nestin)
Diseases named in the same sentence as NES in open-access papers (continued):
Sharing a sentence is not in itself a finding about the gene and the disease.
cancer (continued). "Inhibition of BMP signaling with the selective antagonist DMH2 caused a decrease in the expression of Id1/Id3 and induced significant growth inhibition of cancer cells expressing Oct4 or nestin." (PMID 24160469, 2013). "Isolated CD44 and CD133 cancer cells also express stem cell regulators Oct4, Sox2, nanog, and nestin." (PMID 24160469, 2013). "Inhibition of BMP signaling decreases expression of Id proteins and suppresses growth of cancer cells expressing Oct4 or Nestin." (PMID 24160469, 2013). "Nestin was expressed in frankly malignant cancer cells in 15 of 20 (75%) NSCLC, which is consistent with prior reports." (PMID 24160469, 2013). "Our studies suggest that cancer cells expressing the stem cell markers Oct4 and nestin represent unique cell populations." (PMID 24160469, 2013). "Other reports have demonstrated that CD133 + cancer cells also express Oct4, nestin, nanog, and Sox2." (PMID 24160469, 2013). "Previous studies have demonstrated the involvement of Nestin in the development of cancer, and have suggested that several types of cancer that present with Nestin-positive tumors have a poor prognosis." (PMID 24137328, 2013). "Nestin expression reportedly correlates with aggressive growth, metastasis, poor prognosis and presence of cancer stem cells (CSCs) in various tumors." (PMID 22580387, 2012). "Nestin protein and mRNA were also expressed in endothelial cells of small-sized vessels near cancer cells." (PMID 22580387, 2012). "Up-regulated proteins in each model included 14-3-3 protein theta and alpha enolase from HOS/143B, and nestin and vimentin from SaOS-2/LM7, all of which have been implicated in cancer progression and metastasis." (PMID 22640921, 2012). "As such, adult Nestin-expressing cells would potentially be more competent for cancer initiation and progression following AP-induced proliferation, as suggested by the expression of Nestin in all grade lesions both in human and in mice." (PMID 22140463, 2011). "In opposite, HN-CICs after Sh-GRP78 lentiviruses infection displayed decreased expression of "cancer stemness" genes (Oct-4, Nanog, and Nestin) but enhanced expression of epithelial differentiation marker, CK18 and Involucrin." (PMID 20979610, 2010). "When transplanted subcutaneously into immunodeficient hosts, p18Ink4c-suppressed p16Ink4a/Arf−/− astrocytes formed malignant tumors that were strongly Nestin-positive, in contrast to controlled p16Ink4a/Arf−/− astrocytes which were not tumorigenic in vivo." (PMID 18394558, 2008). "Additionally, nestin has already been recognized as a specific stem cell marker in certain cancers, including brain, pancreatic, prostate, and bladder cancers, contributing to poor prognosis and outcomes." (PMID 40799240, 2025). "This review summarizes the latest research progress of nestin in MM, including the characteristics of nestin, its role in CSCs across different cancers, the current status and cutting-edge detection technologies of MMSC, involved signaling pathways and clinical relevance in MM." (PMID 40799240, 2025). "Several studies have shown that nestin has been proven to be a marker for CSCs in various cancers." (PMID 40799240, 2025). "Cancer stem cells express Nestin and, upon differentiation, this expression decreases." (PMID 36975539, 2023). "To test this hypothesis at the phenotypic level we stained an independent archival series of brain metastasis with the neuronal marker Nestin and we scored the percentage of positive cancer cells." (PMID 37046805, 2023). "Although future large-scale prospective studies should be conducted to verify our findings, incorporating nestin expression into the cancer histologic analysis may be of significance for the prediction of prognosis in some patients with DTCs." (PMID 37485559, 2023). "First, it has been discovered that nestin is expressed in cancer stem-like cells and poorly differentiated cancer cells, suggesting that it may play a role in these cells' aggressive behavior." (PMID 37015965, 2023).
cancer (continued). "Because nestin gets phosphorylated at Thr-315 in cancer cells during proliferative response, we questioned whether contractile activation induces nestin phosphorylation at this residue." (PMID 37316833, 2023). "However, several studies have reported that nestin is a marker of cancer stem cells (CSCs) expressed in malignancies of various organs, including the lung." (PMID 37509714, 2023). "Nestin is originally found to be expressed in progenitor cells of the nervous system, and subsequently its expression has been found to be elevated in several different malignant tumors." (PMID 35370458, 2022). "In addition, a previous study also noted that CD133 and Nestin were cancer cell stemness markers, whereby CD133 and Nestin overexpression was correlated with worse prognosis in terms of overall survival." (PMID 35419917, 2022). "As an upstream regulator of Nestin, miR-204-5p may inhibit cancer cell proliferation and induce cancer cell apoptosis in esophageal squamous cancer cells." (PMID 35370458, 2022). "The overexpression of nestin could also be observed in many cancers including PC, which is thought to be involved in cancer invasion and metastasis." (PMID 35652096, 2022). "Observations in several malignancies suggest that nestin may serve as a central organizer of important processes for cancer behavior." (PMID 34943921, 2021). "Moreover, the knockout of nestin in A549 and H1299 cell lines enhanced cancer cell apoptosis and inhibited cell proliferation and invasion and colony formation." (PMID 34943921, 2021). "As for cancer, nestin exists in cancer stem-like cells and poorly differentiated cancer cells." (PMID 34872521, 2021). "Furthermore, from recent research, the role of nestin has been amplified to show that it is also a CSC marker in different forms of cancer, like brain tumors, ovarian, glioblastoma, lung tumors, and head and neck cancers." (PMID 33919917, 2021). "Extensive studies have revealed that nestin is also a putative marker for cancer stem cells (CSCs)." (PMID 32467665, 2020). "One reason could be that nestin expression was heterogeneous in cancer tissues, resulting in a higher expression rate in surgical specimens that yield larger tissues compared to biopsy specimens." (PMID 32903755, 2020). "Nestin is also expressed in several types of cancers, and also by CD133+ brain CSCs." (PMID 33260962, 2020). "Additionally, the nestin insufficiency poses effects on focal adhesion and cell migration, especially in the context of cancer." (PMID 33396266, 2020). "Recently, nestin has been detected in cancers arising from various lineages." (PMID 32903755, 2020). "In addition to be a common marker of multipotent stem cells, Nestin is also widely upregulated under conditions of tissue injury and cancer development." (PMID 31695040, 2019). "In the same study, we also observed that the antioxidant capacity of cancer cells decreased significantly upon ablation of Nestin expression, indicating that Nestin might participate in the regulation of oxidative stress." (PMID 31695040, 2019). "Our findings suggest that the Nestin–Nrf2 signaling pathway and antioxidant defenses could be targeted as promising therapeutic approaches for cancer treatment." (PMID 31695040, 2019). "SRY-Box 10 (SOX10) induced nestin expression regulates cancer stem cell properties of TNBC cells." (PMID 30175120, 2018). "Moreover, our analysis of several other cancer cell lines showed that Nestin universally underwent nuclear translocation in cancer cells." (PMID 30190500, 2018). "Importantly, nestin is also considered a marker of cancer stem cells from neuroepithelial, epithelial, mesenchimal, and even germ cell origin, and it is used as a prognosis marker for cancer progression." (PMID 29030904, 2018). "Since Nestin is discussed to play a role in cell survival and proliferation of cancer and stem cells, one might expect that expression of Nestin in GBM is associated with patients' survival." (PMID 29535786, 2018).
cancer (continued). "Nestin expression in cancer cells was immunohistochemically studied in 90 patients with completely resected stage II and stage IIIA NSCLC treated with AC and its association with clinicopathologic parameters, including ABCG2, E-cadherin, and vimentin expression, was evaluated." (PMID 28358810, 2017). "Several studies reported that nestin is a putative marker of the cancer stem cell (CSC) phenotype." (PMID 28358810, 2017). "Moreover, these cells, when cotransplanted with the Nestin+/CD133+ cancer cells, promote and accelerate the initiation and growth of orthotopic brain tumor xenografts." (PMID 26880981, 2016). "For Nestin, there was only one meta-analysis examining the associations of Nestin protein expression with TNM in regardless of cancer types." (PMID 27150062, 2016). "In addition, endothelial cells can interact specifically with Nestin+/CD133+ cancer cells, located in proximity of capillaries, and participate in the maintenance of their self-renewing and undifferentiated state, supplying with secreted factors." (PMID 26880981, 2016). "Nestin is a class VI intermediate filament protein that is overexpressed in certain cancers." (PMID 27412382, 2016). "Nestin has been found to be overexpressed in several types of cancers." (PMID 25371063, 2015). "Nestin is overexpressed in cancer and is correlated with nodal metastasis and cancer invasiveness." (PMID 25371063, 2015). "Nestin exhibits stemness characteristics and is over-expressed in several types of cancers." (PMID 25371063, 2015). "Thus, the aim of this study was to evaluate literature reports on the relationship between nestin and cancer stage." (PMID 26015397, 2015). "Nestin was found to modulate metastasis in cancer and cell migration was inhibited by nestin-shRNA." (PMID 25371063, 2015). "Expression of Nestin was weakened in cancer cells forming SK-MES tumors from IL-27-treated mice." (PMID 25638163, 2015). "Furthermore, in the multivariable Cox regression analysis, nestin expression was an independent prognostic factor for cancer-specific survival (HR, 2.45; p = 0.04)." (PMID 24785714, 2014). "However, in view of our findings, the role of nestin needs to be considered in clinical diagnosis and as a potential new target for cancer therapy." (PMID 24966803, 2014). "MB-derived CD133/Nestin double-positive cells (MB-DPs) exhibit cancer stem-like cell (CSC)-like properties that may contribute to chemoradioresistance, tumorigenesis and recurrence." (PMID 24945311, 2014). "They proposed that Nestin expression is crucial for colonizing distant sites in metastasis and thus may be a marker of metastasis-initiated “cancer stem cells”." (PMID 24625091, 2014). "Thus, the precise mechanisms of nestin positive cancer cells action in the proliferation and metastasis of ESCC require further elucidation." (PMID 24966803, 2014). "Immunostaining of tissue specimen for Nestin may therefore be of use as a prognostic marker to evaluate the extent of vessel maturation in cancer specimens." (PMID 25019063, 2014). "However, in view of these findings, the role of nestin needs to be considered in ongoing clinical diagnosis or as a new target for cancer therapy." (PMID 24498263, 2014). "Furthermore, we show that NeuN is frequently expressed in NSCLC and provide evidence suggesting that Oct4 cells give rise to cancer cells expressing nestin and/or NeuN." (PMID 24160469, 2013). "The finding that melatonin affects the expression of Nestin suggests that melatonin may have an effect on stem cell differentiation which promotes the development of cancer." (PMID 24137328, 2013). "By IHC, approximately 3% of the cancer cells from the Oct4/GFP tumors expressed Nestin and NeuN." (PMID 24160469, 2013). "The level of expression of Oct4 and/or nestin in cancer cells may induce specific survival mechanisms." (PMID 24160469, 2013). "The percentage of cancer cells expressing Nestin was from < 1% to 3%." (PMID 24160469, 2013).
cancer (continued). "Nestin expression has been reported in the angiogenic endothelium of cancers." (PMID 23028390, 2012). "Screening of several key proteins controlling cell cycle, development, metabolism, apoptosis and growth, including Erk, Akt, GSK3β, p16 and p14, Bcl-2, c-Myc, Nestin and Sox2, showed that downregulation of Bmi1 reduced GSK3β protein levels and induced differentiation in cancer cells." (PMID 19823589, 2009). "Furthermore, a subset of early Kras-mutant cell-states exhibit marked similarity to either the benign or malignant fates that emerge weeks to months later; for instance, Kras-mutant Nestin-positive progenitor-like cells display accessible chromatin near genes active in malignant tumors." (PMID 37167403, 2023). "In addition, most of the C3 signals were localized in LMSCs, which were marked by Nestin, suggesting that C3 may also be produced by LMSCs in cancer patients." (PMID 34707103, 2021). "Furthermore, Nestin seems to correlate with malignancy in several different cancer types." (PMID 32158431, 2020). "The levels of nestin may serve as indicator of cancer status." (PMID 33171868, 2020). "In addition, nestin was reported to be related to cancer stem cell phenotypes." (PMID 32903755, 2020). "Moreover, the expression of nestin increases in neoangiogenic blood vessels, injury and cancer." (PMID 33396266, 2020). "All of these data suggest that targeting nestin may be a viable therapeutic option in cancer." (PMID 31126068, 2019). "Furthermore, to explore the functions of TGIF1 in regulating cancer stem cell (CSC) properties, we compared the expression levels of stemness transcriptional factors, such as Sox2, Nanog, CD44, Nestin, and CD133, between the TGIF1-deficient PDAC cells and TGIF1-sufficient PDAC cells." (PMID 31109321, 2019). "Therefore, nestin provides a link between CSCs and EMT, and overexpression of nestin may play a role in cancer metastasis." (PMID 25371063, 2015). "Similarly, the expression of BRY and NESTIN at mRNA level may be activated aberrantly in these cells as often observed in cancer cells." (PMID 21785609, 2011). "The intermediate filament Nestin and the stem cell (SC)-transcription factor SOX2 have been shown to play a role in the maintenance of CSC features in different cancer entities." (PMID 41129070, 2026). "Using a mouse cancer cell line (FP10SC2), they observed that Nestin inhibited the interaction of other structural proteins within the cell, leading to diminished cell stiffness." (PMID 40660628, 2025). "Bidirectional regulation of Nestin and NRF2 proves the complexity of redox homeostasis in cancer cells and points toward potential use of this pathway for purposes in the treatment of cancers." (PMID 39941813, 2025). "The knockdown of nestin promoted an increase in the phosphorylation of PI3K, AKT, and mTOR, enhancing the drug resistance of cancer cells." (PMID 40799240, 2025). "Overexpression of NF-YAx activates key genes -Nestin, SOX2, Nanog- that lead to selection of NB cancer stem cells." (PMID 36707502, 2023). "In another study, treating cancer stem cells (CSC) derived from the LN18 GBM cell line with ATRA, inhibited the expression of Nestin and induced cell differentiation through the activation of the extracellular signal-regulated kinase 1/2 (ERK1/2)." (PMID 35889829, 2022). "Supporting this cancer stem cell theory, new evidence suggests that GBM cells often show overexpression of common neural progenitor-cell markers such as nestin, CD133 and CD163." (PMID 35269752, 2022). "Medulloblastoma cancer stem cells (CSC) are defined by the expression of several stem cell markers, including CD133, CD15, and nestin." (PMID 35409174, 2022). "We noticed that the protein expression of nestin (NES), which is typically overexpressed in cancer cells, was significantly enhanced in response to Ftx overexpression; while it was attenuated in response to Ftx silencing." (PMID 35490216, 2022).
cancer (continued). "Although no universally accurate markers for GBM stem cells exist, among the most frequently used markers for detection of GBM cancer stem-like cells, are SOX2 and Nestin." (PMID 36038950, 2022). "The molecular regulation of cancer stemness-related biomarkers/regulators (BMI1, NES, and c-Met) was also examined in OECM1 cells." (PMID 35563887, 2022). "Western blotting indicated that the level of Nestin protein in esophageal squamous cancerous cells and ESCC tissues was higher than in esophageal epithelial cells and para-carcinoma tissues." (PMID 35370458, 2022). "Nestin mRNA expression exhibited a reverse trend with miR-204-5p expression in the comparison between ESCC and para-carcinoma tissues, as well as between ESCC cells and esophageal epithelial cells." (PMID 35370458, 2022). "The results indicated there were 19 Nestin-related miRNAs that were significantly differentially expressed between ESCC tissues and adjacent para-carcinoma tissues." (PMID 35370458, 2022). "As demonstrated in the top DEGs, specifically cancer stem lineage clusters expressed high levels of stemness feature genes including ALDH1A1, PROM1, and NES, while ductal lineage cluster expressed high levels of ductal markers such as MMP7, TSPAN8, and SOX9." (PMID 34732701, 2021). "They express cancer stem cell markers, such as CD34, MMP2, nestin, and SOX2, as well as the astro-neuronal lineage markers GALC, TUBB3 (CD56), and OLIG2." (PMID 34638987, 2021). "Cancer stem cells are defined by the expression of a set of different markers such as CD133, CD44, and Nestin." (PMID 33925297, 2021). "Potential relationships with the expression of tumoral PD-L1 and cancer stem cell (CSC) markers (NANOG, SOX2, OCT4, Nestin and Podoplanin (PDPN)) are assessed." (PMID 34201050, 2021). "Significance of AR expression was correlated with prognostic biomarkers including cancer stem cell markers (CD44, CD24, and ALDH1), basal markers (CK5, CK14, and nestin), proliferation marker (ki-67), apoptotic marker (Bcl-2), and COX-2." (PMID 32850312, 2020). "Using immunofluorescence analysis, the protein expression of Nestin, Sox2, Vimentin, and GFAP was analyzed in these primary cancer cell lines." (PMID 32742192, 2020). "GSCs express both embryonic and neural progenitor cancer stem cell markers, including SOX2, nestin, and CD133." (PMID 32430842, 2020). "However, the mechanistic contributions of Nestin to cancer pathogenesis are still unknown." (PMID 30190500, 2018). "qPCR analysis showed increased expression of many CSC marker genes such as ALDH1, ABCG2, NESTIN, EpCam and CD90, altogether suggesting that hTERT plays a significant role in the expression of cancer and CSC markers." (PMID 29907642, 2018). "It was reported in many studies that miR-940 was highly expressed in normal tissues compared with tumors, and miR-940 was shown to inhibit the migratory and invasive potential of cancer cells by suppressing CXCR2, MIEN1, MyD88, Nestin, and ZNF24." (PMID 28423620, 2017). "We also detected other cancer stem cell-related genes in the putative A549 stem cells, and found that CXCR4, NESTIN, BMI1 gene levels had increased." (PMID 28881812, 2017). "IQGAP1+ staining was observed in neurons (Map2+ cells), in cancer stem cells (CSC; nestin+) and in several macrophages (CD31+ or Iba1+)." (PMID 28098764, 2017). "qPCR analysis showed increased expression of many cancer stem cell marker genes such as ALDH1, ABCG2, CD90, NESTIN, PTEN, and EpCam." (PMID 29115987, 2017). "In NB tumours, it has been shown that cancer stem cells can be identified and purified by virtue of their expression of a number of cell-surface markers, with CD133 and nestin used most frequently." (PMID 29203817, 2017). "In this study, several of the differentially expressed molecules identified, including TGFBI, NES, SNCA, and HSPA12A, have demonstrated roles in GBM and other cancers." (PMID 29228611, 2017).